PDE4C (phosphodiesterase 4C)
Description:
Hydrolyzes the second messenger cAMP, which is a key regulator of many important physiological processes.
Synonyms: DPDE1; PDE21
Tractability: Small molecule: an approved drug acts on it; a high-quality ligand is known; it has a binding pocket of medium quality; it belongs to a druggable protein family. PROTAC: it is named in the literature on targeted protein degradation; a small molecule that binds it is known.
Target class: Phosphodiesterase 4C; Phosphodiesterase; Phosphodiesterase 4; Enzyme
Gene: Protein-coding gene on chromosome 19 (18,207,965 to 18,248,200, reverse strand). Ensembl gene ENSG00000105650.
Subcellular location: Cell projection, cilium
Subcellular location (Human Protein Atlas): Basal body; Centrosome; Cytosol; Midbody ring
Pathways (Reactome):
Signal Transduction: DARPP-32 events; G alpha (s) signalling events
Gene Ontology:
Molecular function: 3',5'-cyclic-AMP phosphodiesterase activity; 3',5'-cyclic-GMP phosphodiesterase activity; 3',5'-cyclic-nucleotide phosphodiesterase activity; phosphoric diester hydrolase activity
Biological process: negative regulation of cAMP/PKA signal transduction; cAMP catabolic process; signal transduction
Cellular component: extracellular region; cilium; cytosol
Genetic constraint (gnomAD): Loss-of-function variants: 51 observed, 61.68 expected, observed/expected ratio (o/e) 0.83, 90% interval 0.66 to 1.04. The upper end of that interval is the gene's LOEUF score, 1.04, which puts it in group 4 of 6, group 1 being the genes least tolerant of losing a copy. Missense variants: 777 observed, 899.13 expected, observed/expected ratio (o/e) 0.86, 90% interval 0.81 to 0.92. Synonymous variants: 377 observed, 389.52 expected, observed/expected ratio (o/e) 0.97, 90% interval 0.89 to 1.05.
Homologues: Orthologues: chimpanzee PDE4C (90% identical), macaque PDE4C (87% identical), dog PDE4C (84% identical), pig PDE4C (82% identical), mouse Pde4c (69% identical), rat Pde4c (69% identical), Drosophila melanogaster Pde8 (19% identical), zebrafish pde11al (19% identical), Caenorhabditis elegans pde-3 (19% identical), Drosophila melanogaster Pde11 (18% identical), Caenorhabditis elegans pde-6 (17% identical), Drosophila melanogaster Pde9 (17% identical), and 1 more. Paralogues in human: PDE4D (69% identical), PDE4A (66% identical), PDE4B (64% identical), PDE1C (24% identical), PDE3A (22% identical), PDE1A (21% identical), PDE1B (21% identical), PDE8A (21% identical), PDE8B (21% identical), PDE3B (21% identical), PDE11A (20% identical), PDE6B (20% identical), and 8 more.
Diseases named in the same sentence as PDE4C in open-access papers:
PDE4C is named in the same sentence as 33 diseases in open-access papers, as found by Europe PMC text mining. Sharing a sentence is not in itself a finding about the gene and the disease. The quoted sentences say what the papers report.
glioma (5 papers, 2015 to 2025). A benign or malignant brain and spinal cord tumor that arises from glial cells (astrocytes, oligodendrocytes, ependymal cells). "Another study has revealed an association in glioma patients between reduced expression of PDE4C and downregulation of apoptotic pathways coupled with upregulation of cell migration pathways by transcriptomic analysis." (PMID 40129976, 2025). "For instance, PDE4A expression is elevated in central nervous system tumor cells, and PDE4B expression in increased in hematologic malignancies, whereas hypermethylation of PDE4C promoter sites was reported in high-grade glioma samples." (PMID 34066000, 2021). "However, PDE4C emerged as the sole prominent member of the PDE4 family in glioma and pancreatic cancer specifically." (PMID 40129976, 2025). "Suppression of PDE4C increased the apoptosis of glioma cells." (PMID 38774995, 2024). "Similarly, high expression of PDE4C was related to shorter survival days in glioma." (PMID 38774995, 2024). "PDE4 consists of four subtypes, PDE4A, PDE4B, PDE4C and PDE4D, and is involved in several human malignancies including prostate cancer, leukemia, colon cancer and glioma." (PMID 34066000, 2021).
lung cancer (3 papers, 2017 to 2025). A malignant neoplasm involving the lung. "In lung cancer, PDE4C is associated with the tumor suppressor miR-542-5p." (PMID 40427523, 2025). "PDE4C is a member of PDE family, while high expression of PDE4C was observed in non‐small cell lung cancer tissues." (PMID 38774995, 2024). "Six genes showed particularly stronger expression pattern in lung cancer tissues, as compared to normal lungs, which demonstrated that these six genes (GABBR1, PDE4B, PDE4C, ADCY6, ADCY1 and GIPR) had more likelihood of being direct targets of miR-542-5p in lung cancers." (PMID 28927388, 2017).
osteosarcoma (2 papers, 2023 to 2024). A usually aggressive malignant bone-forming mesenchymal neoplasm, predominantly affecting adolescents and young adults. "The results showed that 79 DEGs affected the prognosis of osteosarcoma, with PDE4C, CFAP44, CARNS1, GREB1L, ROF207 identified as significant risk factors and GBP1, MSC, GBP3, F13A1, CCL2 as substantial protective factors." (PMID 37796192, 2023).
Papillary Thyroid Carcinoma (2 papers, 2024 to 2025). "We found that the patients with more aggressive forms of papillary thyroid carcinoma, such as CCVPTC, exhibited up-regulated PDE4C expression and down-regulated PDE4A/B/D expression compared with PTC and FVPTC." (PMID 38514754, 2024).
adrenocortical carcinoma (1 paper, 2020). "An acquired variant in PDE4C (p.A291G; COSV53206356) was also reported in an adrenocortical carcinoma among 41 adult cases analyzed by WES." (PMID 32098292, 2020).
brain cancer (1 paper, 2025). A primary or metastatic malignant neoplasm affecting the brain. "Heightened promoter methylation of PDE4C coupled with a reduction in PDE4C protein expression was inversely correlated with overall patient survival rates in brain cancer." (PMID 40129976, 2025).
Cognitive impairment (1 paper, 2025). Abnormal cognition is characterized by deficits in thinking, reasoning, or remembering. "Dio alleviates hypoxia-induced brain damage by modulating the cAMP signaling pathway and regulating the expression of key genes, such as PDE4C, thereby preventing and controlling cognitive impairment." (PMID 40430556, 2025).
growth disorders (1 paper, 2022). "Eleven of the 22 analysed CpGs in the genes PDE4C, ELOVL2 and RPA2 exhibited significant differences between young, healthy individuals and age- and sex-matched individuals with growth disorders." (PMID 35551445, 2022).
hepatoblastoma (1 paper, 2024). Hepatoblastoma (HB) is a malignant hepatic tumor and is the most common pediatric liver cancer. "Hepatoblastoma tumor cells exhibited upregulation of purine metabolism through enhanced expression of ENTPD1, PDE4C, PDE5A, and PAPSS1." (PMID 39684755, 2024).
keloid (1 paper, 2024). An irregularly shaped, elevated mark on the skin caused by deposits of excessive amounts of collagen during wound healing. "The analysis of PDE4 subtypes showed PDE4B the most overexpressed in keratinocytes from hypertrophic scars and keloids followed by PDE4D expression and in a lesser extent by PDE4A and PDE4C." (PMID 39223490, 2024).
muscle atrophy (1 paper, 2024). The loss of muscle tissue due to inactivity or disease. "It remains to be determined whether the absence of PDE4C activity in skeletal muscle using PDE4C inhibitors can promote an increased muscle mass in the absence of an identifiable muscle disease or improve muscle atrophy in clinical neuropathies and myopathies." (PMID 38473107, 2024).
myelodysplastic syndrome (1 paper, 2025). A clonal hematopoietic disorder characterized by dysplasia and ineffective hematopoiesis in one or more of the hematopoietic cell lines. "Notably, elevated PDE4C expression is strongly associated with lower survival and poorer treatment outcomes in a variety of malignant tumors, such as myelodysplastic syndromes (MDS), pancreatic cancer, and lung cancer." (PMID 40129976, 2025).
myeloid malignancies (1 paper, 2020). "Alternatively, we analyzed an age-associated genomic region within the gene PDE4C (26 neighboring CpG sites), which was recently demonstrated to reflect clonal growth in myeloid malignancies." (PMID 32138773, 2020).
schizophrenia (1 paper, 2024). A major psychotic disorder characterized by abnormalities in the perception or expression of reality. "We next explored whether PDE4A, PDE4B, PDE4C, and PDE4D are differentially expressed not only in the brain samples but also in blood samples of patients with schizophrenia and thus might serve as biomarkers." (PMID 38790238, 2024).
cancer (4 papers, 2022 to 2025). A tumor composed of atypical neoplastic, often pleomorphic cells that invade other tissues. "Mounting evidences suggest that the PDE4C is associated with a variety of diseases, including cancer." (PMID 40129976, 2025). "The Human Protein Atlas (HPA) provides comprehensive and significant insights into the expression of PDE4C across different types of cancer." (PMID 40129976, 2025). "As described in HPA, PDE4C exhibited harmful effects in five types of cancer: renal carcinoma, glioblastoma, pancreatic carcinoma, melanoma, and breast cancer." (PMID 40129976, 2025). "The expression levels of PDE4A, PDE4B and PDE4D were down-regulated in THCA patients at different cancer stages, while the expression level of PDE4C was significantly up-regulated." (PMID 38514754, 2024). "Recent studies point to a relationship between PLA2G1B and PDE4C with cancer." (PMID 35379165, 2022). "PDE4C and APOC1 were predicted as key mediators for the crosstalk between M2 macrophage and cancer cells." (PMID 38774995, 2024). "Following calculating high abundance genes in M2 macrophages and cancer cells, we found that PDE4C and APOC1 was both highly enriched in M2 macrophages and cancer cells." (PMID 38774995, 2024).
tumor (4 papers, 2024 to 2025). "PDE4C was highly expressed in THCA tumor tissues, and correlation analysis revealed a positive correlation between PDE4C and LINC02560 and a negative correlation between PDE4C and miR-505-5p." (PMID 40427523, 2025). "In summary, the role of PDE4C in tumors appears to be highly heterogeneous, and further research is warranted to clarify its potential as both a tumor biomarker and a therapeutic target." (PMID 40129976, 2025). "Furthermore, PDE4C has been identified as a crucial intermediary in communication between tumor cells and immune cells." (PMID 40129976, 2025). "Through localization analysis, it was determined that M2 macrophages exhibited the highest expression levels of PDE4C and APOC1, while tumour cells displayed comparatively lower levels." (PMID 38774995, 2024). "To further clarify the potential role of PDE4C in THCA occurrence and development, we analyzed the expression trend of PDE4C mRNA in TCGA-THCA based on the GSCA database, finding significant differences in THCA tumor tissues." (PMID 40427523, 2025).
infection (1 paper, 2025). The state of being infected such as from the introduction of a foreign agent such as serum, vaccine, antigenic substance or organism. "A markedly up-regulation of the PDE4C gene was found in A549 cells following infection with the retS mutant." (PMID 40557319, 2025). "We found that the expression of PDE4C was significantly reduced in cells infected with the ΔretSΔclpV12 and ΔretSΔcupC strain compared to those infected with the ΔretS strain for 12 h post-infection." (PMID 40557319, 2025).
neuromuscular disease (1 paper, 2024). "Finally, identification of possible new disease-causing genes such as PDE4C may lead to the identification of new therapies to reverse muscle atrophy in people and animals with neuromuscular diseases." (PMID 38473107, 2024).
PDE4C also shares sentences with these, for which no sentence is quoted: asthma (1 paper); bacterial infections (1); bladder cancer (1); breast carcinoma (1); ciliary dyskinesia (1); congenital myotonia (1); depression (1); lupus (1); Muscle Hypertrophy (1); myopathies (1); neuropathies (1); pancreatic cancer (1); pulmonary fibrosis (1); steatosis (1); thyroid carcinoma (1).